HDGF (heparin binding growth factor)
Description:
[Isoform 1]: Acts as a transcriptional repressor. Has mitogenic activity for fibroblasts. Heparin-binding protein. [Isoform 2]: Does not have mitogenic activity for fibroblasts. Does not bind heparin. [Isoform 3]: Has mitogenic activity for fibroblasts. Heparin-binding protein.
Synonyms: HMG1L2
Tractability: Small molecule: it has a high-quality binding pocket. Antibody: UniProt places it where antibodies can reach, with high confidence; its Gene Ontology location is reachable by antibodies, with medium confidence. PROTAC: UniProt records ubiquitination sites on it; ubiquitination databases record sites on it; its protein half-life has been measured.
Gene: Protein-coding gene on chromosome 1 (156,742,109 to 156,766,925, reverse strand). Ensembl gene ENSG00000143321.
Subcellular location: Nucleus (Isoform 1); Cytoplasm; Secreted, extracellular exosome; Nucleus (Isoform 2); Nucleus (Isoform 3)
Subcellular location (Human Protein Atlas): Nucleoplasm; Predicted to be secreted
Pathways (Reactome):
Cellular responses to stimuli: XBP1(S) activates chaperone genes
Gene Ontology:
Molecular function: RNA binding; transcription corepressor activity; transcription corepressor binding; heparin binding; DNA-binding transcription repressor activity, RNA polymerase II-specific; RNA polymerase II cis-regulatory region sequence-specific DNA binding
Biological process: negative regulation of transcription by RNA polymerase II; chromatin remodeling; signal transduction; positive regulation of transcription by RNA polymerase II; protein localization to nucleus
Cellular component: cytoplasm; extracellular region; nucleoplasm; nucleus; transcription repressor complex
Genetic constraint (gnomAD): Loss-of-function variants: 5 observed, 26.56 expected, observed/expected ratio (o/e) 0.19, 90% interval 0.097 to 0.4. The upper end of that interval is the gene's LOEUF score, 0.4, which puts it in group 1 of 6, group 1 being the genes least tolerant of losing a copy. Missense variants: 195 observed, 284.46 expected, observed/expected ratio (o/e) 0.69, 90% interval 0.61 to 0.77. Synonymous variants: 122 observed, 107.44 expected, observed/expected ratio (o/e) 1.14, 90% interval 0.98 to 1.32.
Homologues: Orthologues: dog HDGF (93% identical), chimpanzee HDGF (90% identical), rabbit HDGF (90% identical), rat Hdgf (89% identical), mouse Hdgf (88% identical), macaque HDGF (88% identical), pig HDGF (84% identical), guinea pig HDGF (80% identical), tropical clawed frog hdgf (62% identical). Paralogues in human: HDGFL1 (50% identical), HDGFL2 (42% identical), PSIP1 (42% identical), HDGFL3 (40% identical).
Diseases named in the same sentence as HDGF in open-access papers:
HDGF is named in the same sentence as 85 diseases in open-access papers, as found by Europe PMC text mining. Sharing a sentence is not in itself a finding about the gene and the disease. The quoted sentences say what the papers report.
gastric cancer (64 papers, 2010 to 2026). A primary or metastatic malignant neoplasm involving the stomach. "Studies have also revealed the association of HDGF expression with clinical outcomes of patients with pancreatic cancer, gastric cancer, hepatocellular carcinoma." (PMID 34376200, 2021). "In gastric cancer patients, higher HDGF expression levels are significantly associated with tumor infiltration, as well as vascular and lymphatic invasion." (PMID 32545762, 2020). "The corresponding residue in HDGF, Arg79 was also found mutated to a threonine in gastric cancer patients." (PMID 31162607, 2019). "Thus, HDGF is suggested to be significantly associated with the malignant characteristics of gastric cancer." (PMID 32545762, 2020). "In addition, as suggested in hepatoma cells, the altered lipid metabolism may also be partially involved in the growth stimulation of gastric cancer cells caused by HDGF." (PMID 32545762, 2020). "The findings suggest that HDGF and TNFα act as independent signaling molecules in the progression of gastric cancer infected by H. pylori." (PMID 40661971, 2025). "In terms of inhibition of cell viability, we observed contradictory effects of HDGF and TNFα on 3-D human gastric cancer organoids that were infected with CagA-GFP-Hp0549." (PMID 37047540, 2023). "Recombinant HDGF and TNFα inhibited the growth and invasion activities in 3-D-gastric cancer organoids." (PMID 37047540, 2023). "For example, METTL3 promotes gastric cancer glycolysis and progression by regulating the m6A modification of hepatoma-derived growth factor (HDGF) mRNA." (PMID 37340443, 2023). "In gastric cancer, HDGF mRNA was modified by m6A under the action of METTL3, and its stability and expression increased after binding with IGF2BP3." (PMID 37582735, 2023). "In bladder cancer, NSUN2 methylates and stabilizes HDGF mRNA 3′UTR (also stabilized by METTL3 in gastric cancer) promoting cancer metastasis." (PMID 37369946, 2023). "METTL3 upregulation in gastric cancer stimulated m6A modification of HDGF mRNA and enhanced HDGF mRNA stability, resulting in elevated tumor angiogenesis and glycolysis." (PMID 38001065, 2023). "Recombinant HDGF and TNFα inhibited the development and invasion of H. pylori-infected gastric cancer differently." (PMID 37047540, 2023). "While TNFα is defined as the upstream partner of HDGF in 2-D gastric cancer cells, in 3-D organoids in culture, HDGF and TNFα are independent signals for development of H. pylori-infected gastric cancer." (PMID 37047540, 2023). "As previously discussed, HDGF expression is fostered via the METTL3/IGF2BP3-HDGF mRNA axis in an m6A-dependent manner in gastric cancer." (PMID 37280679, 2023). "Further studies are required to examine the roles of both HDGF and TNFα in organoid viability and invasion capacity for gastric cancer progression and to identify the signaling pathways in H. pylori infection." (PMID 37047540, 2023). "Using this organoid system, we provide evidence against the signaling pathways of TNFα and HDGF to develop gastric cancer." (PMID 37047540, 2023). "TNFα is defined as the upstream partner of HDGF in gastric cancer cells in 2-D culture; however, in (3D) organoids in culture, HDGF and TNFα are involved in independent signals in the development of H. pylori-infected gastric cancer." (PMID 37047540, 2023). "To clarify the role of HDGF and TNFα secreted from H. pylori-infected cancer organoids, we prepared recombinant HDGF and TNFα and measured the cytotoxicity and invasion of gastric cancer organoids." (PMID 37047540, 2023). "For instance, the m6A reader IGF2BP3 recognizes and binds to the m6A site on HDGF mRNA, thereby enhancing the stability of HDGF mRNA in gastric cancer." (PMID 36257938, 2022). "Mettl3 is involved in the modification of m6A RNA, and its high expression in gastric cancer tissues promotes the mRNA binding of m6A and HDGF (a growth factor)." (PMID 36438836, 2022).
gastric cancer (continued). "Similar studies in gastric cancer cells showed that METTL3 promotes m6A modification of the mRNA of recombinant protein hepatoma-derived growth factor (HDGF), whereas IGF2BP3 directly recognizes and binds to the m6A site on HDGF mRNA, enhancing its stability." (PMID 36064747, 2022). "For example, METTL3 stimulates the m6A modification of HDGF mRNA to increase its expression and then trigger the glycolysis in gastric cancer cells." (PMID 35832094, 2022). "CCNI2 promoted the progression of human gastric cancer through HDGF, which drew further interest regarding its clinical application as a potential therapeutic target." (PMID 34895232, 2021). "Our study found that HDGF overexpression exhibited a significant promotion in the progression of gastric cancer cells." (PMID 34895232, 2021). "Hepatoma-derived growth factor (HDGF) mRNA is a key downstream target of METTL3 in gastric cancer (GC)." (PMID 34858499, 2021). "Since there was a relationship between CCNI2 and HDGF, their biological functions in gastric cancer cell lines deserved further investigation." (PMID 34895232, 2021). "Studies on the critical roles of HDGF in various cancers, including pancreatic cancer, gastric cancer, hepatocellular carcinoma, have matured." (PMID 34376200, 2021). "HDGF stimulated the differentiation of neutrophils in gastric cancer patients and relayed Hp-induced inflammatory signaling, which was involved in gastric carcinogenesis." (PMID 34021184, 2021). "HDGF is an important oncogene involved in proliferation, invasion, and metastasis in liver cancer, stomach cancer, prostate cancer, and non-small cell lung cancer." (PMID 34959221, 2021). "In the following, taking gastric cancer as an example, METTL3 can promote the development and progression of gastric cancer by mediating m6A RNA modification of HDGF mRNA." (PMID 34660577, 2021). "HDGF is expressed in gastric cancer cells, and the reduction of HDGF in gastric cancer cells induced apoptotic signaling and reduced the invasive activity of the cells." (PMID 32545762, 2020). "METTL3, which expression is correlated with poor prognosis, promotes gastric cancer cell proliferation and liver metastasis by stimulating m6A modification of heparin binding growth factor (HDGF) mRNA." (PMID 33372610, 2020). "Recently, increasing numbers of studies have also supported the possible involvement of HDGF in the disease progression of gastric cancer." (PMID 32545762, 2020). "HDGF expression is reported to positively correlate with lymph node metastasis and prognosis of gastric cancer, acts as a prognostic factor for gastric cancer." (PMID 30513684, 2018). "HDGF recruits HBMMSCs, and then HBMMSCs further contributes to cell survival and invasive motility in human gastric cancer cells." (PMID 30513684, 2018). "In the present study, we demonstrated that H. pylori infection promotes HDGF expression in human gastric cancer cells." (PMID 30513684, 2018). "HDGF is closely involved in the disease progression of gastric cancer, which substantially affects the prognosis." (PMID 30513684, 2018). "It has shown that HDGF stimulates the growth of several types of cancer cells such as HuH-7 hepatoma cells, gastric cancer cells and melanoma." (PMID 29300772, 2018). "(ii) H. pylori infection induces HDGF expression in the human gastric tissue and human gastric cancer cells." (PMID 30513684, 2018). "In gastric cancer cells, miR-141 reduced cell motility by targeting hepatoma-derived growth factor (HDGF)." (PMID 24992595, 2014). "Notably, highly expressed METTL3 promotes gastric cancer (GC) cell liver metastasis by stabilizing HDGF mRNA via m6A." (PMID 41446042, 2025). "In addition, it was reported that TNFα growth factor secreted from H. pylori infected gastric cancer cells was the upstream target factor of HDGF." (PMID 37047540, 2023).
gastric cancer (continued). "In addition, the effects of hepatoma-derived growth factor (HDGF) and tumor necrosis factor (TNFα) on the growth and invasion activity of H. pylori-infected gastric cancer organoids were examined." (PMID 37047540, 2023). "To clarify the role of HDGF and TNFα secreted from H. pylori, we prepared recombinant proteins of HDGF and TNFα and added them into the organoid cultures, and the cytotoxicity of gastric cancer organoids." (PMID 37047540, 2023). "Thus, we propose that HDGF and TNFα are independent signals for development of H. pylori-infected gastric cancer." (PMID 37047540, 2023). "H. p. infection also promoted the expression of HDGF in human gastric cancer cells." (PMID 35053302, 2022). "In gastric cancer, higher expression of METTL3 is associated with poor prognosis, and mechanistically, METTL3 mediates the m6A modification of HDGF mRNA in a manner with IGF2BP3-dependent HDGF mRNA stability." (PMID 35541906, 2022). "Furthermore, a study also suggested that overexpression of METTL3 facilitated gastric cancer liver metastasis and angiogenesis in vivo, which correlated with methylation states of secreted heparin-binding growth factor (HDGF)." (PMID 35937999, 2022). "As a consequence, we clarified that HDGF can promote the malignant progression of gastric cancer." (PMID 34895232, 2021). "Knockdown of CCNI2 alleviated the promoting effects of HDGF overexpression in gastric cancer cells." (PMID 34895232, 2021). "In gastric cancer (GC), METTL3 can cause m6A to accumulate on HDGF mRNA, which indicates proliferation and poor prognosis and enhances the stability of zinc finger MYM-type containing 1 (ZMYM1) mRNA so that it accelerates epithelial-mesenchymal transition (EMT) and metastasis." (PMID 32303268, 2020). "HDGF contributes to the proliferation and metastasis of gastric cancer." (PMID 33228740, 2020). "METTL3 has been reported to promote gastric cancer angiogenesis by secreting HDGF." (PMID 32211315, 2020). "HDGF can promote tumor angiogenesis, and nuclear HDGF activates the expression of GLUT4 and ENO2 which are associated with proliferation and liver metastasis of gastric cancer cells." (PMID 33552994, 2020). "HDGF contributed to the proliferation and metastasis of gastric cancer." (PMID 32266933, 2020). "Therefore, HDGF is considered as an independent prognostic factor in patients with hepatocellular carcinoma, gastric cancer, pancreatic cancer, non–small-cell lung cancers, and gastrointestinal stromal tumors." (PMID 30513684, 2018). "It was reported that methyltransferase-like 3 (METTL3)-mediated m6A modification of HDGF mRNA promotes gastric cancer (GC) progression and has prognostic significance." (PMID 36866236, 2023). "Therefore, we preliminarily determined that HDGF was regulated by CCNI2 in gastric cancer and may be a downstream target of CCNI2." (PMID 34895232, 2021). "Additionally, we studied the regulation mechanism of CCNI2 on gastric cancer and found that HDGF may be the downstream of CCNI2." (PMID 34895232, 2021). "Thus, CCNI2 promote the development and progression of gastric cancer through HDGF, which may be a therapeutic target for gastric cancer." (PMID 34895232, 2021). "Besides, knockdown of CCNI2 could alleviate the promoting role of HDGF overexpression in gastric cancer cells." (PMID 34895232, 2021). "However, the mechanism behind HDGF-mediated gastric cancer development requires verification." (PMID 30513684, 2018). "HDGF could stimulate the proliferation of fibroblast, vascular smooth muscle cells, endothelial cells and a variety of cancer cell lines including hepatoma, melanoma, lung cancer gastrointestinal stromal tumors, pancreatic cancer, and gastric carcinoma." (PMID 23536873, 2013). "Studies have found that METTL3 upregulates the m6A level of heparin binding growth factor (HDGF) mRNA, and then enhances its stability and promotes its expression through IGF2BP3, thereby increasing tumor angiogenesis and promoting gastric cancer metastasis." (PMID 40356596, 2025).
gastric cancer (continued). "In gastric cancer cells, METTL3 stimulates the m6A modification of heparin binding growth factor (HDGF) mRNA, and IGF2BP3 then directly binds to the m6A-modified mRNA and enhanced RNA stability." (PMID 37192910, 2023). "In gastric cancer, METTL3 stabilizes hepatoma-derived growth factor (HDGF) that activates GLUT4 and ENO2 expression and subsequent angiogenesis and glycolysis that promote liver metastasis." (PMID 37369946, 2023). "In gastric cancer, IGF2BP3 directly recognizes and binds to the m6A site on HDGF mRNA and enhances its stability." (PMID 37298373, 2023). "Previous studies indicated that in human gastric cancer cells, high expression of METTL3 stimulates the expression of GLUT4 and ENO2 via the METTL3/HDGF axis, thereby promoting tumor angiogenesis and glycolysis." (PMID 36347025, 2022). "Subsequently, HDGF up-regulates the expression of GLUT4 and other key proteins, thus promoting aerobic glycolysis in gastric cancer cases." (PMID 36438836, 2022). "To understand this issue in detail, we have investigated the close relationship between H. p. infection and HDGF/TNF-α signaling using organoids from normal human gastric tissues and from gastric cancers." (PMID 35053302, 2022). "In gastric cancer (GC), METTL3 promotes cell proliferation and liver metastasis in GC by enhancing m6A modification and stability of HDGF." (PMID 36008805, 2022). "Nuclear HDGF activates Glucose transporter-4 (GLUT4) and ENO2 expression, followed by the acceleration of glycolysis in gastric cancer (GC) cells, which subsequently results in liver metastasis." (PMID 34211849, 2021). "For example, in gastric cancer, METTL3 promotes the pathogenesis by catalyzing the methylation of ZMYM1 or HDGF." (PMID 34489709, 2021). "Hepatoma-derived growth factor (HDGF) is a vital promoter of many cancers, including liver cancer, stomach cancer, and lung cancer, by regulating proliferation, metastasis, and invasion of cells." (PMID 33345275, 2021). "HDGF is also involved in cell proliferation, anti-apoptosis and VEGF expression in human gastric cancer." (PMID 30513684, 2018). "The results demonstrated that H. pylori infection induces HDGF expression, HDGF upregulates CAF markers in HBMMSCs, and recruits HBMMSCs; in which HBMMSCs promoted gastric cancer cell survival and invasive motility." (PMID 30513684, 2018). "HBMMSCs were pretreated with HDGF (1 ng/mL) for 24h for differentiating into CAF-like cells, and then co-cultured with human gastric cancer cells." (PMID 30513684, 2018). "Hepatoma-derived growth factor (HDGF) plays a critical role in tumor cell proliferation, anti-apoptosis, VEGF expression, lymph node metastasis and poor prognosis in human gastric cancer." (PMID 30513684, 2018). "The level of miR-141 showed an inverse correlation with the protein expression of hepatoma-derived growth factor (HDGF) in gastric cancer cells, and overexpression of miR-141 negatively regulated the proliferation and invasion of gastric cancer cells." (PMID 25425543, 2014). "Increased HDGF expression appears to correlate with the proliferating states of several cancer types hence it may be used as a novel prognostic factor for melanoma, gastrointestinal stromal tumors, esophageal carcinoma, pancreatic cancer, lung cancer and gastric carcinoma." (PMID 23536873, 2013). "Additionally, METTL3 could promote angiogenesis and metastasis in gastric cancer (GC) and bladder cancer through regulating m6A and mRNA stability of hepatoma-derived growth factor (HDGF), tyrosine kinase endothelial (TEK) and VEGFA, respectively." (PMID 38322265, 2024). "Additionally, in gastric cancer, IGF2BP3 directly recognizes the m6A site on HDGF (Heparin Binding Growth Factor) mRNA, a process initiated by METTL3." (PMID 38902779, 2024). "HDGF in the nucleus can combine with the promoters of GLUT4 and ENO2, increase the content of glycolytic enzymes in cells, and promote glycolysis, proliferation and liver metastasis of gastric cancer." (PMID 37582735, 2023).